GRIA3 (glutamate ionotropic receptor AMPA type subunit 3)
Diseases named in the same sentence as GRIA3 in open-access papers (continued):
Sharing a sentence is not in itself a finding about the gene and the disease.
status epilepticus (3 papers, 2019 to 2025). Status epilepticus is defined as a continuous seizure lasting more than 30 min, or two or more seizures without full recovery of consciousness between any of them. "We show that the epileptic phenotype associated to GRIA3 haploinsufficiency may manifest with refractory myoclonic status epilepticus, though the proband demonstrated an overall ameliorative evolution, becoming seizure-free from the age of 14." (PMID 34731330, 2022).
Ataxia (2 papers, 2017 to 2022). Ataxia refers to impaired coordination of voluntary muscle movement. "Compared to the uninjured mice, we found that the mRNA expression levels of Gria3, Gria4, Grin2b, and Grin2c were markedly increased in DCN at day 7 post-SNC in non-ataxia control and ataxia mice." (PMID 36064798, 2022).
hepatocellular carcinoma (2 papers, 2014 to 2026). A malignant tumor that arises from hepatocytes. "In the current study, we demonstrate that HIF-dependent GRIA2 and GRIA3 expression in hepatocellular carcinoma and ccRCC cell lines promotes tumor progression through effects on proliferation, survival, migration and invasion." (PMID 25326682, 2014). "We next analyzed the prognostic implication of the HIF regulated genes involved in glutamate signaling in hepatocellular carcinoma (SLC1A1, SLC1A3, GRIA2, GRIA3 and FYN) using PROGgene to analyze the GSE 10141 mRNA expression data set from 80 surgically resected hepatomas." (PMID 25326682, 2014).
autism (1 paper, 2019). Persistent deficits in social interaction and communication and interaction as well as a markedly restricted repertoire of activity and interest as well as repetitive patterns of behavior. "Importantly, de novo missense variants affecting the M3 channel gate or the M3-S2 linkers have been previously identified in several iGluR subunit genes (e.g., GRIA1, GRIA3, and GRIA4); phenotypes of these patients include ID, autism and epilepsy." (PMID 31300657, 2019).
autism spectrum disorder (1 paper, 2022). A spectrum of developmental disorders that includes autism, and Asperger syndrome. "As to autism spectrum disorders and behavioural issues, also described in individuals with GRIA3 deleterious variants, our patient did not express autistic traits whereas he occasionally showed oppositional conduct and aggressive outbursts." (PMID 34731330, 2022).
diabetes (1 paper, 2013). "Diabetes did not change GRIA2 and GRIA3 mRNA expression possibly because photoreceptors, bipolar cells, and amacrine cells were less likely to be affected by glutamate excitotoxicity than ganglion cells." (PMID 23878504, 2013). "In contrast, diabetes did not alter the expression of GRIA2 and GRIA3 flip at either 4 or 12 weeks (p>0.02)." (PMID 23878504, 2013). "In this study, diabetes did not change the expression of GRIA2 and GRIA3." (PMID 23878504, 2013).
injury (1 paper, 2025). Damage inflicted on the body as the direct or indirect result of an external force, with or without disruption of structural continuity. "To determine the functional significance of the GluA3 abundance in neuropathic pain and spinal cord CP-AMPARs induced by nerve injury, we intrathecally injected Gria3-expressing lentiviruses or control lentiviruses in sham and SNL rats 2 weeks after surgery." (PMID 41129242, 2025).
liver fibrosis (1 paper, 2024). "Additionally, the highly expressed genes GRIA3, FABP4, FADS2, and PRKAA2 have been implicated in lipid metabolism and liver fibrosis." (PMID 38263097, 2024).
lung adenocarcinoma (1 paper, 2019). A carcinoma that arises from the lung and is characterized by the presence of malignant glandular epithelial cells. "We found that overall survival and relapse free survival was significantly shorter in lung adenocarcinoma patients with low GRIA3 expression than in their counterparts with high GRIA3 expression." (PMID 31498117, 2019). "Low GRIA3 expression correlated with poor prognosis in lung adenocarcinoma patients." (PMID 31498117, 2019).
nematode infection (1 paper, 2019). "Two sub-units of NMDARS, NR2A and NR2B (also known as Grin2A and Grin2B) as well as several AMPARs including the metabotropic glutamate receptors 1 and 2 (mGlu-R1 and mGlu-R2), Gria3, Grm2, Grm4, Grik3 and Grik5 were up-regulated in the pup brain on P7 in response to maternal nematode infection." (PMID 30862816, 2019).
Nicotine addiction (1 paper, 2025). "Among these, the TGF-beta signaling pathway, T cell receptor signaling pathway, and Nicotine addiction pathway were highly enriched (p < 0.01) enriched involving relevant genes (PITX2, ID4, BMP4, DLG1, IKBKB, ICOS, GRIA3, and SLC17A6)." (PMID 40496916, 2025).
X-linked intellectual disability (1 paper, 2022). An X-linked intellectual deficiency in which not enough information is known, reported or published to indicate whether a gene causes non-syndromic or syndromic presentations. "The deletion of GRIA3 and CUL4B genes are the cause of X-linked mental retardation or/and X-linked intellectual disability." (PMID 36329552, 2022).
tumor (10 papers, 2012 to 2024). "A recent study showed that the knockdown of GRIA3 significantly reduced the proliferation and migration of tumor cells and enhanced apoptosis." (PMID 39684655, 2024). "The SPI was calculated based the prognostic model, including BOC, GRIA3, MME, SPOCK1, and KNSTRN, which were associated with stemness, TNM stage, prognosis, and tumor microenvironment (TME)." (PMID 35360859, 2022). "In terms of upregulated DEGs, seven genes (ABI3BP, CTSG, DPP4, CCL18, OSR2, GRIA3, MMP2) demonstrated reduced expression in tumor compared to normal tissue." (PMID 39062832, 2024). "The underlying mechanism indicates that miR-330-3p targets GRIA3 to mediate the interaction between GRIA3-TGF-β1, resulting in EMT, tumor proliferation, migration, and invasion." (PMID 34281588, 2021). "Among these, we found some tumor suppressor genes (e.g. H19, ACTN4) that were down-regulated and some genes related to tumor progression and metastasis formation (e.g. ENPP2, GRIA3, TPM3) that were up-regulated." (PMID 23049808, 2012). "Interestingly, upregulated DEGs like SNCG (logFC 9.95), CPNE8 (logFC 7.18), GRIA3 (logFC 4.08), SOX5 (logFC 3.94) and CRISP3 (logFC 3.44) representing the highest log fold changes were involved in tumor cell metastasis and invasiveness." (PMID 37239828, 2023).
cancer (5 papers, 2014 to 2023). A tumor composed of atypical neoplastic, often pleomorphic cells that invade other tissues. "The most significantly upregulated DEGs such as SNCG, CPNE8, GRIA3, SOX5 and CRISP3 can be involved in metastasis and invasivity of cancer cells as well." (PMID 37239828, 2023). "Analyzing gene expression data from 42 ccRCCs in the International Cancer Genome Consortium revealed that SLC1A1, GRIA3 and FYN mRNA abundance was each significantly correlated with the expression of six known HIF target genes." (PMID 25326682, 2014).
neurodegenerative disease (3 papers, 2017 to 2025). A disorder of the central nervous system characterized by gradual and progressive loss of neural tissue and neurologic function. "The gene GRIA3 encodes the GluA3 subunit of the AMPA receptor, which is widely associated with neurodevelopmental disorders and is a synaptic marker of neurodegenerative diseases." (PMID 39739972, 2024).
neurological diseases (3 papers, 2014 to 2023). "In addition, there was some overlap in genetic targets associated with cognitive function and neurological disease (e.g., GRIA3 and GRIN1) in one study that analyzed 8–10 weeks male mice brain tissue 4 h after exposure to 0.1 or 2 Gy." (PMID 25147559, 2014). "The genes with the highest number of connections with other diseases were PAK3, GRIA3, and ADGRB1 associated with eight, six, and six neurological diseases, respectively." (PMID 33922640, 2021).
neurodevelopmental disorder (2 papers, 2024 to 2025). A behavioral and cognitive disorder with onset during the developmental period that involves impaired or aberrant development of intellectual, motor, or social functions. "GRIA3 gene mutations seem to result in a broad spectrum of neurodevelopmental disorders with heterogeneous epileptic manifestations." (PMID 41462794, 2025).
GRIA3 also shares sentences with these, for which no sentence is quoted: frontotemporal dementia (6 papers); non-small cell lung carcinoma (3); dementia (2); infection (2); Obesity (2); alcohol abuse (1); Allan-Herndon-Dudley syndrome (1); amyotrophic lateral sclerosis (1); aneurysm (1); atherosclerosis (1); Atrophy (1); autoimmune encephalitis (1); brain ischemia (1); clear cell renal cell carcinomas (1); cognitive disorder (1); colorectal cancer (1); Danon disease (1); dementia with Lewy bodies (1); developmental epileptic encephalopathy (1); encephalitis (1); Encephalopathy (1); Lesch-Nyhan syndrome (1); Liver Disease (1); migraine with aura (1); neuroblastoma (1); neuronal migration disorders (1); oesophageal cancer (1); Parkinson disease (1); premature ovarian failure (1); Seizure (1).
A further 3 diseases each share a sentence with GRIA3 in 1 paper.